IL4 (interleukin 4)
Diseases named in the same sentence as IL4 in open-access papers (continued):
Sharing a sentence is not in itself a finding about the gene and the disease.
gastric cancer (continued). "In the present study, we investigated the association between IL4 VNTR gene polymorphism and risk of gastric cancer in a South Indian population." (PMID 26383107, 2015). "Most down-regulated genes, such as p27 are also repressed in all other gastric cancer cell lines, while some of the listed genes, such as IL4 Stat, are more intensively down-regulated in gastric cancer cells of peritoneal dissemination." (PMID 12402156, 2002). "In addition, xCELL immunoinfiltration analysis was performed on the gastric cancer RNA-seq data of TCGA, and it was found that M2 macrophage infiltration increased and Th1 and Th2 cell infiltration decreased with the activation of IL-4/IL-4R axis." (PMID 39003253, 2024). "In addition, to further confirm the role of IL-4/IL-4R axis in gastric cancer, analysis of TCGA data showed that high expression of IL-4R was correlated with poor OS and PFS in patients with gastric cancer." (PMID 39003253, 2024). "This is consistent with the results of previous studies that added GLP that 400 mg/kg GLP reduced serum levels of IL-1β and IL-6 in diabetic rats, and 800 mg/kg GLP reduced serum IL-6 and TNF-α levels and increased serum IL-2, IL-4, and IL-10 levels in rats with gastric cancer." (PMID 39457856, 2024). "This suggests that IL-1β may have a synergistic effect with IL-4 in promoting immunotherapy resistance of gastric cancer through macrophages." (PMID 39003253, 2024). "Furthermore, patients with secondary resistance are accompanied by elevated IL-4 expression, therefore, we conclude that high levels of IL-4 lead to gastric cancer anti-PD-1 immunotherapy resistance." (PMID 39003253, 2024). "Moreover, the serum IL-6 and TNFα levels were decreased, and the serum IL-2, IL-4 and IL-10 levels were increased in gastric cancer mice after tea polysaccharides treatment." (PMID 36505461, 2022). "In MNNG gastric cancer rat model, administration of 50, 100 or 150 mg/kg body weight of lycopene caused an increment in antioxidant enzymes as expected (SOD, CAT, GSH-Px) and increment in cytokines (IL-2, IL-4, IL-10, TNF-α) and antibodies (IgG, IgA, IgM)." (PMID 34202203, 2021). "Similarly, a higher prevalence of IL-4 −590T and IL-4 −33TT genotypes was identified among the intestinal-type gastric cancer patients." (PMID 34484153, 2021). "Increasing reports have identified various downstream genes of miR-320a including programmed cell death protein 1 (PD1) in malignant mesothelioma, interleukin 4 in preeclampsia, microtubule-associated protein 9 (MAP9) in postmenopausal osteoporosis, and Rab protein 14 (RAB14) in gastric cancer." (PMID 34720057, 2021). "Conversely, in gastric cancers increased levels of both serum IL-10 and IL-4 have been reported." (PMID 32298379, 2020). "Our data indicated that acupuncture and moxibustion promotes a typical Th1 cells drifting by upregulating T-bet/IFN-γ and downregulating GATA3/IL-4, enhancing immune inhibition of advanced gastric cancer which originally exhibits predominant expression of Th2 type cytokines." (PMID 33144870, 2020). "After culture in vitro for a week, lymphocytes isolated from H. pylori-infected gastric cancer tissues (Hp+) displayed a vigorous ability to secrete IL-4 and an impaired function of IFN-γ secretion, when compared to those isolated from the H. pylori-uninfected individuals (Hp−)." (PMID 29138530, 2017). "High expression of IL-4 resulted in worse survival rate of breast and gastric cancer patients." (PMID 27895317, 2016). "Our data showed that the mRNA expression levels of the transcription factors RORα and GATA3, the receptors T1/ST2 and IL-17RB, surface markers CRTH2, and type 2 cytokines IL-33, IL-5, and IL-4 were significantly increased in PBMCs from patients with gastric cancer compared to healthy controls." (PMID 24741632, 2014). "The anti-inflammatory effects of FFKSIL may be related to IgA, IgM, IgG, IL-6 and TNF-α production and IL-2, IL-4 and IL-10 reduction in gastric cancer rats." (PMID 22728348, 2012).
gastric cancer (continued). "In the previous study on the molecular mechanism of the action of Elian granules on precancerous lesions of gastric cancer through network pharmacology, we found that the active components of Elian granules can regulate the activation factors of M2-type macrophages, such as IL-4 and IL-10." (PMID 37291549, 2023). "Gastritis (n=58) and gastric cancer (n=31) patients were evaluated and compared with H. pylori-positive asymptomatic controls (n=46), for serum antibodies against recombinant HP-NAP and IL-4 C-590T single nucleotide polymorphism using immunoblotting and PCR-RFLP, respectively." (PMID 27677314, 2017). "In a mouse gastric cancer model, increased TGF-β and IL-4 promoted IL-9 secretion by Th9 cells, inhibiting tumor-associated inflammation and metastasis." (PMID 40909266, 2025). "At the same time, IL-4 and IL-4R were highly expressed in tumor tissues, while in the public database, MSIscore and TMB in gastric cancer tissues were decreased with the increase of IL-4 and IL-4R expression." (PMID 39003253, 2024). "Professor Chang-Ming Huang and colleagues confirmed that in gastric cancer, CDK5RAP3 inhibited nuclear transcription of NF-κB, thereby decreasing the secretion of cytokines IL4 and IL10 and blocking the polarization of M2 macrophages." (PMID 38643190, 2024). "Rescue studies have shown that neutralizing antibodies to IL4 and IL10 can attenuate the upregulation of CD206+ macrophages induced by gastric cancer cells with low CDK5RAP3 expression." (PMID 35999359, 2023). "We identified that IL4 and IL10 were significantly enriched in the KEGG ‘cytokine-cytokine receptor interaction pathway’, which is significantly activated in gastric cancer with low CDK5RAP3 expression." (PMID 35999359, 2023). "In contrast, the levels of IL4 and IL10 in the culture supernatant increased significantly in CDK5RAP3-depleted gastric cancer cells, while PDTC reduced the upregulation of IL4 and IL10 levels induced by gastric cancer cells with low CDK5RAP3 expression." (PMID 35999359, 2023). "The levels of IL4 and IL10 were significantly reduced in gastric cancer cells overexpressing CDK5RAP3." (PMID 35999359, 2023). "The neutralizing antibodies against IL4 and IL10 also reduced the upregulation of CD86+ macrophages induced by the overexpression of CDK5RAP3 in gastric cancer cells." (PMID 35999359, 2023). "We found that production of the cytokines tested (IL-2, IL-4, IL-6, IL-10, IFN-γ) were up-regulated after exposure to gastric cancer derived exosomes." (PMID 32901082, 2020). "In the light of existing controversies, the aim of present study is a comprehensive comparative analysis of IL-4 and IL-13 expression at mRNA and protein level, local and systemic, in CRC as compared to esophageal and gastric cancers." (PMID 32512917, 2020). "Compared with the normal control rats, blood IL-2, IL-4, IL-10 and TNF-α levels were significantly reduced in the gastric cancer model rats, while blood IL-6 level was significantly increased." (PMID 21686188, 2011). "In this study, blood IL-2, IL-4, IL-10 and TNF-α levels in gastric cancer model control rats were significantly lower than those in normal control rats." (PMID 21686188, 2011). "Lycopene treatment had significantly increased blood IL-2, IL-4, IL-10, TNF-α levels and reduced the IL-6 level in gastric cancer rats." (PMID 21686188, 2011). "Concerning the linkage between cytokines and the HADS-D score, only IFN-γ (P = 0.049), but not IL-4 (P = 0.065) or IL-17A (P = 0.058), was positively linked to the HADS-D score in elderly gastric cancer patients." (PMID 36386524, 2022). "Quantification of circulating IL-4, TNF-α, IL-10 and INF-γ level in 17 patients diagnosed with gastric carcinoma and 30 subjects as control population was achieved by ELISA assay (Affymetrix Ebioscience, USA) using a calibration curve with known concentration standard (as described)." (PMID 30526523, 2018).
gastric cancer (continued). "Stratification analysis of IL4 VNTR genotype frequencies, ORs and 95% CIs in Gastric cancer." (PMID 26383107, 2015). "In addition, 15×19 CAR T cells did not produce IL-4, IL-10, or IL-17A cytokines upon stimulation by gastric cancer cells." (PMID 36618357, 2022). "IL-6 can impair Th1 differentiation through stimulating IL-4/IL-21 production and therefore has negative impacts on antitumor responses by shifting Th1/Th2 balance to Th2 dominance, leading to unfavorable prognosis in a wide range of tumor types including gastric cancer." (PMID 33144870, 2020). "Moreover, it should be emphasised that the high counts of GATA3+ lymphocytes in gastric mucosa may be the consequence of a IL-4 driven T-helper-2-cell differentiation of CD4+ T cells, a mechanism described in the context of H. pylori infection and that could influence gastric cancer pathogenesis." (PMID 32575504, 2020).
lung carcinoma (57 papers, 2010 to 2025). "We also recognize IL-4 produced in the tumor microenvironment as the causative signal mediating the epigenetic TAP2 silencing in lung cancer." (PMID 40091029, 2025). "Those associated with lung cancer include interleukin-4 (IL-4), IL-6, monocyte chemotactic protein-1 (MCP-1), and tumor necrosis factor-alpha (TNF-α)." (PMID 39042180, 2024). "Other factors closely linked with inflammation in lung cancer include IL-1β, IL-4, IL-8, IL-11, IL-12, monocyte chemotactic protein (MCP)-1, and TGF-β." (PMID 38539448, 2024). "Our literature mining also supports a role for the decoy inhibitory protein, IL-18BP as being a mediator of lung cancer risk as well as IL-10, IL-12, IL-4 and TNF31." (PMID 38527997, 2024). "Cytokine gene single nucleotide polymorphisms (SNPs) of interleukin (IL)-1β, IL-4, and IL-16 genes have been reported to be associated with the risk of cancers, including renal cell carcinoma, gastric carcinoma, and lung cancer." (PMID 36034203, 2022). "Third, other risk factors (occupational exposures, physical activity etc.)were not included and should be considered to be assessed in the future and more comprehensive analyses about IL‐4 polymorphisms in lung cancer are needed to confirm the results." (PMID 30729744, 2019). "In this study, we performed a case‐control study to evaluate the association between SNPs distributed in the IL‐4 gene and lung cancer susceptibility in a Chinese population." (PMID 30729744, 2019). "In the present hospital‐based case‐control study, we investigated the association between six single nucleotide polymorphisms in the IL‐4 gene and lung cancer risk in the Chinese male populations." (PMID 30729744, 2019). "In conclusion, we demonstrated that rs2243250, rs2243267, and rs2227284 in IL‐4 gene are associated with a decreased risk of lung cancer in northwestern Chinese males." (PMID 30729744, 2019). "We next examined IL-4, IL-5, IL-6, and IL-13 levels in BAL, since IL-4, IL-5, and IL-13 are major mediators of allergic inflammation and IL-6 gene polymorphisms have been associated with increased lung cancer risk in asthmatics." (PMID 20796309, 2010). "However, the overall information about association between IL‐4 polymorphisms and lung cancer risk is poor." (PMID 30729744, 2019). "Moreover, IL-4 polymorphisms have been found linked with the risk of lung cancer." (PMID 35153741, 2021). "Comparable responses in TAP2, SOCS1 levels and surface peptide-HLA complexes after IL-4 treatment were observed in PC9 lung cancer cells." (PMID 40091029, 2025). "It is envisioned that IL-4 signaling can also induce effects beyond TAP2 downregulation in lung cancer cells." (PMID 40091029, 2025). "For example, in lung cancer, TBX21 affects the progression of the tumor and the prognosis of patients by promoting the self-renewal and survival ability of lung cancer stem cells through the activation of the IL-4 signaling pathway." (PMID 41573646, 2025). "The cytokines produced by “Type 2” immune cells (including ILC2s), IL-5, IL-13 and IL-4, were increased in both PLs and mPEs from lung cancer patients as compared to HD PLs." (PMID 40993215, 2025). "IL-4, released by Th2 lymphocytes, is involved in regulating the immune response and has been found in high expressions in lung cancer." (PMID 38539448, 2024). "Inflammatory cytokines related to lung cancer include IL-1β, IL-4, IL-6, IL-11, IL-12, TNF-α, monocyte chemotactic protein (MCP)-1, and TGF-β." (PMID 35898583, 2022). "A recent study in lung cancer proposed that IL-12 secretion was in part inhibited by IL-4 signaling in cDC110." (PMID 35418195, 2022). "One report demonstrates that 15-PGDH is activated by IL-4 in association with JAK/STAT6, MAPK, PI3K, and PKC signaling in lung cancer cells." (PMID 34194517, 2021). "Th1 (IFN-γ) or Th2 (IL-4 and IL-10) cytokines responsible for M1 or M2 macrophage polarization were detected in malignant pleural effusions of lung cancer patients in a previous study." (PMID 33175182, 2021).
lung carcinoma (continued). "This is similar to prior reports where in vitro differentiation to dendritic cells by GM-CSF/IL-4 was inhibited by soluble factors secreted by lung cancer cells, and suggests that monocyte differentiation in tumors is skewed towards CD68+ macrophages." (PMID 33069212, 2020). "It was reported that RAW264.7 activated by IL-4 and LPS promoted the growth of lung cancer in a mouse model." (PMID 31291948, 2019). "In conclusion, our findings indicate that IL-4/STAT6 signaling in CD11b+ cells promotes lung cancer progression by triggering an IL-4 positive feedback loop and increasing M2 myeloid cells." (PMID 31798581, 2019). "The goal of this study was to investigate the association between interleukin‐4 (IL‐4, OMIM#147780) single nucleotide polymorphisms (SNPs) and lung cancer susceptibility." (PMID 30729744, 2019). "IL4 has been found to act as an autocrine survival factor in epithelial cells from colon, breast, and lung carcinomas." (PMID 23451142, 2013). "The IL-4 and IL-13 stimulated the lung cancer cell A549 to secrete CCL26." (PMID 41294800, 2025). "In addition, exposure of lung cancer cells to IL-4 suppressed the increase in TAP2 protein induced by IFNγ or IFNγ + TNFα." (PMID 40091029, 2025). "The IL-4 and IL-13 further stimulated the lung cancer cell A549 to secrete CCL26." (PMID 41294800, 2025). "The use of IL-4 cytotoxin was suggested as a new therapeutic strategy for treating lung cancer." (PMID 39125732, 2024). "IL-4: IL-4 receptors were found to be present in lung cancer." (PMID 39125732, 2024). "Ten blood cytokine levels, including; granulocyte-macrophage colony-stimulating factor, TNF (alpha), and IFN (gamma), IL1, IL6, IL12, IL4, IL8, IL10, IL5, were compared between 296 European-Americans and 170 African-Americans to determine their associations with lung cancer." (PMID 36874133, 2023). "Because EML4-ALK interacted with the JAK2-STAT pathway resulting in the phosphorylation of STAT proteins in EML4-ALK-positive lung cancer cells, we investigated whether IL4 or IL6 activated the JAK2-STAT pathway in these cells." (PMID 34090412, 2021). "Moreover, by promoting the expression of multiple target genes, including DDIAS, cyclin D1, IL-2, and IL-4, NFATc1 protects lung cancer cells against anticancer drug-induced death." (PMID 33859351, 2021). "In lung cancer for instance, certain cytokines (IL-4, IL-5, IL-8, IL-10, IFN-γ, and TNF-α) were significantly elevated among EA compared to AA patients, whereas elevated IL-1β, IL-10, and TNF-α levels were associated with lung cancer only among AA patients." (PMID 32714862, 2020). "Additionally, LD block was constructed with six SNPs in IL‐4, and we found that the CGGACA haplotype was related to a significantly decreased lung cancer susceptibility." (PMID 30729744, 2019). "Of note, we found greater levels of inflammatory factors such as IL‐4, IL‐10 and TGF‐β were associated with a higher CYP2E1 level in peritumoral tissues, indicating that CYP2E1 may be related to the inflammation response in lung cancer." (PMID 37875398, 2023). "Collectively, these results reveal that IL-4 reduces TAP2 expression, mimics the effects of TAP2 downregulation and mediates adaptive immune evasion of human lung cancer cells." (PMID 40091029, 2025). "The study measured the concentration of IFN-γ, TNF-α, IL-1β, IL-2, IL-4, IL-6, IL-10, and IL-12p70, in venous blood and BALF of a total of 33 patients with lung cancer and 33 patients with benign lung diseases." (PMID 37373987, 2023). "Postoperative IL-6, IL-4, and IFN-γ changes have been suggested as prognostic markers in lung cancer surgery." (PMID 35898583, 2022).
lung carcinoma (continued). "The PI3Kγ inhibitor AS-605240, another top candidate, was found to suppress lung carcinoma inflammation and the secretion of pro-inflammatory cytokines (e.g. IL-17, IFN-γ, IL-22, GM-CSF, IL-6, IL-4, and IL-13)." (PMID 33381110, 2020). "For lung cancer, high intra-tumoral concentrations of CXCR2 ligands (CXCL1, CXCL5, and CXCL8) and type 2 cytokines IL-4, IL-5, IL-10, and IL-13 have been reported for non-small cell lung cancer." (PMID 26231039, 2015). "Treg cells could inhibit the activation of T lymphocytes by secreting cytokines such as IL-4, IL-10, and TGF-β, which regulate the immune function of tumor patients and promote the proliferation of lung cancer cells." (PMID 33879165, 2021). "Our results showing a synergistic interaction between IL-4 and LPS on the release of TSLP from human lung macrophages might have translational relevance in the context of lung cancer." (PMID 34440780, 2021). "USP17 could be induced by cytokines secreted from macrophages because various cytokines, including TNF-α, IL-1β, IL-4, IL-6, IL-8, IL-10, CXCL12, CCL18, and CCL22, were able to induce USP17 expression in H1299 and D121 lung cancer cells." (PMID 30038267, 2018). "In addition, with the advent of a new monoclonal (Dupilumab) that blocks the shared receptor for Il-4 and IL-13 used in COPD patients with type 2 inflammation, the inflammation driving both COPD and lung cancer may help prevent the disease." (PMID 40149288, 2025). "IRF1 is downregulated in lung cancer, IPF and PAH datasets, probably because it represses the expression of genes involved in anti-proliferative response, such as BIRC5/survivin, CCNB1, CCNE1, CDK1, CDK2 and CDK4 and in immune response, such as FOXP3, IL4, ANXA2 and TLR4." (PMID 31867044, 2019).